CCL2 (C-C motif chemokine ligand 2)
Diseases named in the same sentence as CCL2 in open-access papers (continued):
Sharing a sentence is not in itself a finding about the gene and the disease.
breast cancer (continued). "Secreted by tumor cells, fibroblasts and immune cells, CCL2 promotes breast cancer growth and spread by several means such as inducing the infiltration of inflammatory monocytes and tumor-associated macrophages, by acting as vascular permeability factor or by inducing angiogenesis." (PMID 37176074, 2023). "Therefore, this study reveals the potential of blocking CXCR2 activation or CCL2 signaling pathway in inhibiting tumor growth and paclitaxel resistance in breast cancer." (PMID 37821959, 2023). "Here, we focus on our analysis of TNC and CCL2 in HER2+-breast cancer." (PMID 37176074, 2023). "Moreover, the specific relation between TNC and CCL2 is also described, as both proteins are involved and highly overexpressed in the case of breast cancer." (PMID 37834140, 2023). "Chemokine (C-C motif) ligand 2 (CCL2), a pro-inflammatory chemokine, has been implicated in breast cancer progression and the expression level of CCL2 is closely correlated with accumulation of tumor-associated macrophages (TAM) and breast cancer metastasis." (PMID 37064130, 2023). "Considering previous reports and our results, we hypothesized that CCL2 could act as a mediator to determine the aggressiveness of EGFR+ HER2+ breast cancer." (PMID 36674955, 2023). "Research implies that CCL2 helps breast cancer cells spread through the body." (PMID 37373025, 2023). "Interestingly, the expression profile of Ccl2, Col1a1, Col1a2, and Itgam was very close to most of the breast cancer samples, with a degree of variability among samples." (PMID 37243196, 2023). "Numerous studies have shown that the overexpression of CCL2 amplifies many cancer cells’ motility and promotes tumor development and metastasis, such as chondrosarcoma, nasopharyngeal carcinoma, and breast carcinoma." (PMID 37893141, 2023). "Moreover, augmented CCL2 expression has a remarkable correlation with poor overall survival and is a predictor of cancer recurrence in breast cancer." (PMID 35408440, 2022). "For example, a recent study revealed that macrophages could be recruited for breast cancer by increasing CCL2." (PMID 35519620, 2022). "It has been demonstrated that CCL2 and its receptor CCR2 are implicated in the development and progression of various malignancies, such as prostate cancer, breast cancer, hepatocellular cancer, lung cancer, renal cancer, pancreatic cancer, and nasopharyngeal carcinoma." (PMID 35702353, 2022). "The purpose of this paper is to review the role of CCL2 in the occurrence and development of gynecological cancers and to discuss the potential therapeutic strategy of CCL2 for gynecological cancers, with a primary focus on breast cancer, ovarian cancer, cervical cancer, and endometrial cancer." (PMID 36403055, 2022). "Similarly, breast cancer metastasis can be promoted by increased recruitment of inflammatory cells in a CCL2-dependent manner, which was suppressed by miR-126/miR-126* in cancer cells." (PMID 36248881, 2022). "Adipocyte-derived chemokine (C-C motif) ligand 2 (CCL-2) plays dual functions in promoting breast cancer development by regulating breast cancer stemness and creating an immunosuppressive environment via the recruitment of macrophages through the CCL-2-IL-1β signaling axis." (PMID 35805056, 2022). "This was also true in another dataset from patients with breast, colorectal, and lung cancer (GSE103512), where mean KRAS/CCL2/IL1B expression was significantly higher in lung and colorectal cancer, which have higher KRAS mutation rates, compared with breast cancer." (PMID 35327394, 2022). "Notably, CDDO-Me has been shown to inhibit both EGF and CCL2, consistent with our prior studies in breast cancer that reported decreased TAM numbers in tumors treated with CDDO-Me." (PMID 35265066, 2022). "Meanwhile, CCL2 overexpression stimulated the proliferation of breast cancer cell line 4T1." (PMID 36403055, 2022).
breast cancer (continued). "However, cessation of CCL2 therapy led to increased and rapid metastasis in multiple pre-clinical mammary tumor models through VEGF-mediated angiogenesis." (PMID 35435599, 2022). "•CCL2/CCR2 signaling in breast cancer cells depend on interactions with MET." (PMID 35405500, 2022). "However, downregulation of cancer cell-derived CCL2 inhibited the interaction between breast cancer cells and Tregs, thus inhibiting the proliferation and migration of breast cancer cells." (PMID 36077785, 2022). "Finally, a variety of chemokines are induced by poly(I:C) exposure, including Ccl2, Ccl5 and Cxcl1 in 4T1 mammary carcinoma cells in a dose-dependent manner." (PMID 35737804, 2022). "The activities of luciferase reporter constructs containing deletion variants of the CCL2 promoter were assessed in MDA-MB-231 breast cancer cells in the presence or absence of TGF-β1 (10 ng/mL, 24 h)." (PMID 34239022, 2021). "Previous studies showed that CCL2 significantly stimulated CCR2 signaling in breast cancer cells." (PMID 33888841, 2021). "Stromal CCL2 signaling in AT may even play a role in promoting fibrosis of mammary tumors through the recruitment of myeloid-lineage cells." (PMID 33540898, 2021). "In preclinical models, macrophages have been shown to orchestrate early breast cancer dissemination and metastasis in a mouse model of HER2+ breast cancer, where CCL2 produced by both cancer cells and myeloid cells recruited CD206+/Tie2+ macrophages to propagate the disease." (PMID 33968034, 2021). "Similarly, in another study with breast cancer lines, CCL2 overexpression by tumor cells promoted cancer metastasis to lung and bone." (PMID 34804061, 2021). "Conversely, we found a downregulation of VLDLR, whose genetic or epigenetic silencing contributes to gastric carcinogenesis, CYP27A1, which induces T cell dysfunction, thus promoting breast cancer progression and CCL2, downregulated in diffuse gastric cancer primarily in advanced stages." (PMID 34012923, 2021). "Interestingly, CAFs from breast cancer patients but not normal human mammary fibroblasts expressed high levels of CCL2 mRNA in response to activation by various breast cancer cells." (PMID 34804061, 2021). "Additionally, CCL2 has been shown to recruit monocytes and macrophages to breast tumors and to facilitate breast cancer metastasis." (PMID 34353349, 2021). "To determine the clinical relevance of CCL2/CCR2 signaling protein expression in breast cancer, we performed immunohistochemistry staining on patient samples of DCIS, IDC and normal adjacent tissues for detection of CCL2, CCR2, phospho-SMAD3 and phospho-42/44MAPK proteins." (PMID 33888841, 2021). "Also, in breast cancer, a high level of monocyte chemoattractant protein 1 (MCP-1, CCL2) in the tumor tissue and in the circulating blood correlates with a poor prognosis." (PMID 35237501, 2021). "CCL2 is a chemokine that play an important role in modulating the pre-metastatic niche by attracting inflammatory monocytes that in turn can favor circulating tumor cell extravasation, thus promoting metastasis formation in breast cancer." (PMID 34090457, 2021). "Furthermore, in vivo, breast cancer cell pulmonary seeding is blocked by three different methods of macrophage depletion and by monocyte recruitment inhibition by CCL2 blockade." (PMID 33783686, 2021). "Vascular wall-resident MSCs as well as hBMMSCs displayed a capacity for decreasing the risk of lung metastasis after radiation-induced injury in breast cancer and melanoma by downregulating endothelial MMP2 and SASP factors CCL2 and Plau/uPA, which were induced by radiation injury." (PMID 33849537, 2021). "CCL2 and CCL5 play important roles in prostate cancer metastasis and drug resistance, while CCL4 is associated with the clinical characteristics of breast cancer." (PMID 33737938, 2021). "CCL2: CCL2 is highly expressed in clinical ER+ breast cancers compared to normal breast epithelium." (PMID 34359625, 2021).
breast cancer (continued). "TAMs are recruited to mammary tumors through induction of a variety of cytokines and chemokines including C-C Motif Chemokine Ligand 2 (CCL2), CCL3, CCL5, Colony Stimulating Facotor-1 (CSF-1/M-CSF), and Granulocyte-Macrophage Colony-Stimulating Factor (GM-CSF or CSF2)." (PMID 34298673, 2021). "Additionally, they showed that this HS mimetic, potentially by binding to CCL2, inhibits breast cancer CCL2-mediated cell proliferation and CCR2/CCL2- mediated cell migration, and it reduces cell invasiveness." (PMID 34858858, 2021). "In a mouse model of basal-like breast cancer, a complex Notch-dependent paracrine loop between tumor cells and TAMs promoted an immunosuppressive tumor microenvironment, regulating the expression of IL-1β and CCL2." (PMID 33840390, 2021). "CCL2 expression is regulated by miR-126/126* in breast cancer cells." (PMID 33868269, 2021). "Furthermore, SMAD3 cooperation with p42/44MAPK was found to be important in CCL2/CCR2 mediated breast cancer cell survival and motility." (PMID 33888841, 2021). "Thereby, TGF-β undoubtedly acts as an activator of CCL2 expression in progressive breast cancer; however, the molecular mechanism of this action remains unknown." (PMID 34239022, 2021). "This hypothesis needs to be further fully investigated and targeting LDHA combined with CCL2/CCR2 antagonists may provide a better therapeutic outcome for breast cancer." (PMID 34178639, 2021). "In breast cancer it was also demonstrated that CCL2 levels were higher in stromal cells derived from tumors compared to normal breast tissues and that fibroblast-derived CCL2 contributed to tumor growth and metastasis in vivo." (PMID 32582148, 2020). "Breast cancer cell-derived supernatant treated neutrophils significantly expressed high levels of interleukin-1β (IL-1β), CC-chemokine ligand-2-4 (CCL2, CCL3, CCL4), inducible nitric oxide synthase (iNOS), and matrix metallopeptidase-9 (MMP9), and formed extracellular traps (NETs)." (PMID 33049964, 2020). "Thus, CCL2 and P65 transcriptional upregulation contribute to a worse prognosis for breast cancer patients." (PMID 32455851, 2020). "Interestingly, in a mouse model of metastatic breast cancer, administration of anti-CCL2 antibody suppressed metastasis, while interruption of CCL2 inhibition caused metastatic overshoot and accelerated death." (PMID 33297571, 2020). "It has been shown that CCL2 is overexpressed in breast cancer cell lines characterized as triple-negative, and silencing its expression led to inhibition of tumor progression depending on blocking the renewal of cancer stem cells and M2 macrophage polarization." (PMID 32887237, 2020). "CCL2 expression is also elevated by radiotherapy in breast cancer, colon cancer, head and neck squamous cell carcinoma, and pancreatic ductal adenocarcinoma, which leads to the resistance of these cells to radiotherapy and causes their migration and then metastasis." (PMID 33182504, 2020). "However, how CCL2 expression increases in breast cancer, particularly in TNBC, is not fully understood." (PMID 32455851, 2020). "In the present model, we further expand the mechanisms of MDSCs to include both the secretion of Arg-I and NO by MDSCs, which inhibit Teff cytotoxicity and induce Treg expansion, and CCL2 secretion by breast cancer cells, which facilitates MDSC recruitment into the tumor." (PMID 32158754, 2020). "Importantly, a survival analysis from cBioPortal dataset demonstrates that the higher CCL2 expression levels are significantly correlated with the poor survival rate of breast cancer patients (p = 0.0202)." (PMID 33244467, 2020). "Altogether these data demonstrated that CCL2 may play pivotal roles during the development of mammary glands and breast cancer progression." (PMID 33244467, 2020). "CCL2 also contributes to the acquisition of tamoxifen resistance in breast cancer cells." (PMID 33297571, 2020).
breast cancer (continued). "Since we observed that P65 and PARP1 interact in breast cancer cells, we wanted to examine whether it is bound at the CCL2 promoter and if the binding is affected due to PARP1 inhibition." (PMID 32455851, 2020). "Indeed, the GEO database analysis demonstrated that the increased expression of S100A14, CCL2 or CXCL5 in primary breast cancer was a determinant of poor metastasis-free survival in patients." (PMID 32483412, 2020). "We now show that PARP1 might be functional in multiple ways to regulate chemokines like CCL2 in breast cancer as well." (PMID 32455851, 2020). "Notably, production of the chemokine CCL2 within breast cancer cells was significantly decreased in conditions where either CD44 was deleted or HA was depleted." (PMID 32455980, 2020). "Thus, PARG inhibition partially rescued PJ34 mediated downregulation of CCL2, suggesting a positive correlation between CCL2 transcription and PARylation in the breast cancer cells." (PMID 32455851, 2020). "CCL2-induced chemokine cascade promotes breast cancer metastasis by enhancing retention of TAMs." (PMID 33297571, 2020). "Our findings illustrated that Notch3 signaling activation is necessary for the development of the mammary gland, but its hyperactivation closely relates to breast cancer progression, and that Notch3-regulating CCL2/CCR4 axis should be the target for breast cancer therapy." (PMID 33244467, 2020). "Although this association is not well studied, in an experiment that was performed using an animal model of HER-2-positive breast cancer, CCL2, which is produced by cancer and myeloid cells, attracted macrophages to upregulate Wnt-1 and downregulate E-cadherin, resulting in cancer dissemination." (PMID 32580398, 2020). "In vitro, knocking down TGFA did not reduce breast cancer cell production of MCSF, but did reduce the expression of CCL2, leading the authors to conclude that breast cancer cell-derived TGFα induced autocrine EGFR signaling, leading to increased CCL2 and macrophage recruitment." (PMID 33069212, 2020). "In addition, Ly6C+CCR2+ monocytes that trigger metastasis of mammary tumors were also found to be higher, which is inconsistent with the expression of CCL2, which is known to enhance the establishment of Ly6C+CCR2+ monocyte-assisted lung metastasis." (PMID 33628730, 2020). "Moreover, it was found that MAPK11 (p38β) activation in breast cancer cells has given rise to elevated CCL2 production, which then contributed to increased bone resorption." (PMID 32582148, 2020). "Additionally, either deleting CD44 or inhibiting HA synthesis decreases inflammatory cytokine (e.g., CCL2) production by breast carcinoma cells." (PMID 32455980, 2020). "In breast cancer patients, elevated levels of CCL2 have been detected in blood serum." (PMID 31208996, 2019). "Compared with healthy volunteers, the extremely high serum levels of MMP-9 and CCL21 in patients with colon cancer, of CCL11 in patients with gastric cancer, of CCL2/MCP-1 in patients with breast cancer and of CXCL13 in patients with liver cancer have been reported." (PMID 31754081, 2019). "Moreover, Lavenderet al.40 reported that intra-tumoral CCL2 enables induction of breast tumor growth and/or metastases in breast cancer metastasis to the lungin vivo." (PMID 32695310, 2019). "However, it has been shown that patients with high CCL2 expressing basal-like, HER2+ and luminal B breast cancer exhibit a higher probability of longer survival in comparison to those patients with low expression of CCL2." (PMID 30873179, 2019). "Moreover, CCL2 inhibition in mammary tumor-bearing mice decreased tumor growth, metastasis, macrophage recruitment, and angiogenesis, suggesting that this cytokine regulates tumor progression via a macrophage dependent mechanism." (PMID 31665136, 2019). "In addition to p42/44MAPK, CCL2/CCR2 activates multiple signaling pathways in breast cancer cells including: PKC, Rho and SRC to regulate growth and motility." (PMID 31208996, 2019).
breast cancer (continued). "In breast cancer, inflammatory monocytes could be continually recruit by CCL2 produced by cancer cells and differentiate into TAMs that facilitate the subsequent growth of metastatic cells." (PMID 30927925, 2019). "Another study has reported that cancer cells may activate CAFs in a paracrine manner, and as a result, several secretory factors such as CCL2, are upregulated, resulting in chemotherapeutic resistance in breast cancers." (PMID 30927911, 2019). "We previously reported that 4T1 murine breast cancer cells produce GM-CSF that up-regulates macrophage expression of several cancer promoting genes, including Mcp-1/Ccl2, Ccl17 and Rankl, suggesting a critical role of cancer cell-derived GM-CSF in cancer progression." (PMID 31888216, 2019). "Our results imply that ZA treatment might reduce the ability of breast cancer cells to enhance the expansion and migration of Tregs by reducing their production of CCL2 and CCL5." (PMID 30808421, 2019). "Because Ccl2 is a well-known monocyte/macrophage recruiting factor in BC24–28, we explored an association between c-Myb immunostaining in tumor cells and TAMs infiltration in clinical specimens of breast carcinomas." (PMID 31406165, 2019). "Thus, our work provided further support that E2-mediated increasing cell proliferation, invasion and angiogenesis are consequences of CCL2 upregulation in ER+ breast cancer cells." (PMID 29934505, 2018). "CCL2-induced chemokine cascade in macrophages contributes to the metastasis of breast cancer, and CCR1 inhibition may be utilised to treat metastatic disease." (PMID 29685151, 2018). "Indeed, CCL2 and CCL11 have been implicated in several cancers, including breast cancer etiology and metastasis." (PMID 29879116, 2018). "Furthermore, it has been observed that human breast cancer cell-derived exosomes induce the secretion of IL-6, TNFα, and CCL2 from both human THP-1 and murine RAW macrophage cell lines via the toll-like receptor 2/NF-κB signaling pathway." (PMID 29867925, 2018). "It is also reported that high expression of a CCR2 ligand (CCL2) in tumors positively associates with the accumulation of TAMs in glioblastoma, squamous cell carcinoma, renal cell carcinoma (RCC), as well as ovarian, endometrial, lung, and breast cancer." (PMID 30483271, 2018). "Furthermore, previous studies have shown both IL-6 and CCL2 are expressed in human breast cancer cell lines and enhance tumor growth, migration, and immune cell recruitment." (PMID 30458886, 2018). "CCL2 expression positively correlated with Twist staining and aggressiveness of breast cancer." (PMID 29934505, 2018). "Here we correlate CCL2 expression to transcription factor Twist using human breast tumor specimens and for the first time identify a mechanism through which estrogenic condition facilitates CCL2 synthesis to promote metastasis and angiogenesis in HR+ breast cancer, to our best knowledge." (PMID 29934505, 2018). "Furthermore, conditioned medium from 4T1 mammary tumor cells can increase CCL2 expression in cultured macrophages." (PMID 30483271, 2018). "Interestingly, cessation of CCL2 inhibition accelerated breast cancer metastasis by promoting the infiltration of bone-marrow monocytes into tumors, indicating the importance of CCL2 signaling in regulating metastatic growth." (PMID 29594035, 2018). "CCL2 can recruit inflammatory monocytes to promote metastasis of breast cancer." (PMID 30723697, 2018). "Our present study also examined the regulatory effects of CCL2 on different breast cancer cells, while disrupting CCL2-CCR2 axis by CCR2 antagonist RS102895 could attenuate these effects partially due to downregulation of MMP-9 and VEGF expression in vitro." (PMID 29934505, 2018). "Overall, the data indicate that in HR-positive breast cancer, hormonal regulation on CCL2 expression might be strongly related to modulation of Twist expression via PI3K/AKT/NF-κB signaling instead of MEK/ERK pathway." (PMID 29934505, 2018).